HAS1 (hyaluronan synthase 1)
Diseases named in the same sentence as HAS1 in open-access papers (continued):
Sharing a sentence is not in itself a finding about the gene and the disease.
HAS1 also shares sentences with these, for which no sentence is quoted: colon cancer (4 papers); mesothelioma (3); esophageal carcinoma (2); lung adenocarcinoma (2); lymph node metastasis (2); adenomyosis (1); atherosclerosis (1); benign epithelial tumors (1); breast invasive carcinoma (1); cervical squamous cell carcinoma (1); cholangiocarcinoma (1); chronic lymphocytic leukemia (1); colon adenocarcinoma (1); colorectal adenocarcinoma (1); ductal carcinoma in situ (1); dysplasia (1); endocervical adenocarcinoma (1); endometrioid endometrial carcinoma (1); glioblastoma multiforme (1); hepatitis C (1); high-grade glioma (1); inflammatory bowel disease (1); Insulin resistance (1); ischemia (1); ischemic stroke (1); kidney chromophobe (1); lung squamous cell carcinoma (1); malignant mesothelioma (1); mammary adenocarcinoma (1); ovarian serous cystadenocarcinoma (1).
A further 8 diseases each share a sentence with HAS1 in 1 paper.